SNORA64 (small nucleolar RNA, H/ACA box 64)
Synonyms: U64; RNU64
Gene: Small nucleolar RNA gene on chromosome 16 (1,962,973 to 1,963,106, reverse strand). Ensembl gene ENSG00000207405.
Gene Ontology:
Molecular function: protein binding
Biological process: RNA processing
Cellular component: nucleolus
Homologues: Orthologues: chimpanzee SNORA64 (99% identical), macaque SNORA64 (98% identical), mouse Snora64 (80% identical), pig SNORA64 (80% identical), rat Snora64 (79% identical), guinea pig SNORA64 (78% identical). Paralogues in human: SNORA10 (61% identical), SNORA10B (61% identical).
Diseases named in the same sentence as SNORA64 in open-access papers:
SNORA64 is named in the same sentence as 6 diseases in open-access papers, as found by Europe PMC text mining. Sharing a sentence is not in itself a finding about the gene and the disease. The quoted sentences say what the papers report.
pancreatic cancer (2 papers, 2025 to 2026). "Small nucleolar RNA H/ACA Box 64 (SNORA64) was presented as a predictive marker for pancreatic cancer stages in our previous study." (PMID 42004856, 2026).
SNORA64 also shares sentences with these, for which no sentence is quoted: acute myeloid leukemia (1 paper); gallbladder cancer (1); non-small cell lung carcinoma (1); prostate carcinoma (1); tumor (1).